EGFR (epidermal growth factor receptor)
Diseases named in the same sentence as EGFR in open-access papers (continued):
Sharing a sentence is not in itself a finding about the gene and the disease.
tumor (continued). "Therefore, further prospective research on a more representative population is warranted to establish possible relationships between kinin receptor expression and other tumor molecular features, such as IDH mutation status, EGFR amplification, PTEN deletions/mutations, and MGMT methylation status." (PMID 38254732, 2024). "Multivariable regression analyses demonstrated that the combination of clinical variables, tumor CT features, and ILA CT features significantly improved the predictive ability, with non-fibrotic ILA and small tumors as significant independent predictive factors for EGFR mutation." (PMID 38783331, 2024). "Several malignancies have been noted to show high or abnormal EGFR expression, thereby precipitating sustained activation and amplification of downstream signaling pathways, stimulating physiological and pathological angiogenesis to enhance blood supply to the tumor." (PMID 38679659, 2024). "Indeed, they considered that inhibition of VEGFR and EGFR was relevant to the function of the genetically modified T cells, favoring tumor infiltration, reducing the immunosuppressive status of the tumor microenvironment, and down-modulating PD-L1 expression in the cancer cells." (PMID 38892318, 2024). "Moreover, EGFR inhibitors have exhibited significant anti-tumor activity against OS." (PMID 38434350, 2024). "In this regard, some groups have also found a correlation between +cCAV1 and a more malignant tumor phenotype, including a strong association with a lack of expression of estrogen receptors, epidermal growth factor receptor (EGFR) overexpression and basal-like biomarkers." (PMID 39596307, 2024). "Moreover, blockade of EGFR/ERK/NFκB and EGFR/PI3K/NFκB signaling not only decreases IL6 and IL6R-associated chemoresistance in OC but also, when combined with an anti-IL6 antibody (Tocilizumab), potentiates the anti-tumor effect." (PMID 39766086, 2024). "An EGFR 19 exon deletion mutation in a patient with this tumor type was detected for the first time by NGS, and our results suggest that the malignant transformation of pulmonary papillary adenoma may be mediated by EGFR mutation." (PMID 38902753, 2024). "In addition, EGFR overexpression and activation enhances PD-L1 expression by tumor cells." (PMID 38804302, 2024). "Hence, it is crucial to investigate the mechanisms underlying acquired resistance to EGFR-TKIs and identify potential therapeutic targets that can restore tumor sensitivity to EGFR-TKIs to improve the efficacy of EGFR-TKI treatment and enhance patient outcomes." (PMID 38397056, 2024). "Aberrant EGFR signaling may lead astrocytes to generate pro‐tumor effects or even tumor entities." (PMID 39722126, 2024). "Moreover, overexpression of EGFR and its signaling pathway components in pituitary corticotroph adenoma was reported; and found to be positively associated with ACTH and cortisol levels as well as tumor recurrence." (PMID 38862897, 2024). "Moreover, abnormal fucosylation in tumors is often linked to the activation of receptors like EGFR and TGF-βR, which affect the functions of integrins, selectins, and apoptotic signaling pathways, ultimately impacting tumor growth, invasion, cell death, and metastasis." (PMID 39684225, 2024). "The ADC, but not cetuximab alone, could induce cell cycle arrest and engender cytotoxic functions specifically against EGFR-high tumor cells, with subsequent release of free payloads to trigger bystander cytotoxicity against neighboring EGFR-low cells in the heterogenic tumor microenvironments." (PMID 38772416, 2024). "Consequently,this enables it to suppress the carcinogenic effect mediated by β‐catenin,effectively overcoming acquired resistance to EGFR‐TKIs caused by MET amplification in both cell line‐derived and patient‐derived tumor xenograft (PDX) mouse models while maintaining exceptional biosecurity." (PMID 38867713, 2024).
tumor (continued). "Emerging evidence indicates that NSCLC may harbor mutated and non-mutated EGFR clones in the same tumor tissue." (PMID 39064005, 2024). "While evidence on EREG and AREG secretion from CAFs in response to EGFR-targeted therapy is limited, it has been shown that EREG and AREG can be overexpressed and secreted from CAFs in colitis-associated CRC as well as other cancer types to promote tumor progression." (PMID 40727266, 2024). "The expression level of PD‐L1 in the tumor microenvironment (TME) and the tumor mutation burden (TMB) could serve as vital indicators for predicting the response to ICIs in NSCLC patients without EGFR mutation." (PMID 39631794, 2024). "Considering that oncogenic activation of the EGFR pathway results in an immune-inert phenotype and recent literature has implicated a potential role of YY1 in mediating tumor immune escape, these conclusions may also be tentatively extrapolated to cancer immunotherapy." (PMID 39604408, 2024). "Taken together, this data suggests that coexisting subpopulations of cancer cells within the same tumor have different levels of sensitivity to targeted inhibitors even in the absence of genomic alterations (e.g., c-Met amplification) known to drive resistance to anti-EGFR treatment." (PMID 39061010, 2024). "No KRAS nor BRAF variants were detected in EGFR-positive tumor samples." (PMID 39063150, 2024). "Similarly, by neutralizing tumor B7-H3 with anti-B7-H3 antibodies, we found that cancer cells significantly increased susceptibility to OXP, leading to caspase-3 cleavage and activation in EGFR-overexpressing cells." (PMID 38370387, 2024). "Therefore, the safety of the combination therapy of PD-1/PD-L1 inhibitors and EGFR-TKI therapy in NSCLC patients remains unclear, possibly related to PD-L1 expression, tumor mutation burden (TMB), and potential differences in different tumors." (PMID 38762484, 2024). "Insights into tumor biology suggest that BRAF mutations contribute to more aggressive disease phenotypes and may influence therapeutic responses, particularly regarding anti-epidermal growth factor receptor antibody treatments in metastatic CRC." (PMID 39119381, 2024). "Consequently, MNB-Pyra Nbs exhibited effective inhibition to EGFR-overexpressed tumor in vivo." (PMID 39138197, 2024). "However, the precise mechanism through which GLUT1 regulates tumor-related signaling pathways and expression of oncogenes such as EGFR remains unclear." (PMID 38831321, 2024). "Of these patients, 613 patients had advanced-stage disease, of which 136 (22%) patients had cEGFRm at diagnosis, 8 (1%) had ex20ins at diagnosis, 338 (55%) had EGFR wild type tumours at diagnosis, and 131 (21%) did not have mutation testing at diagnosis conducted at the UHN-PMCC." (PMID 38668049, 2024). "These therapeutic properties could further benefit from the ability of cetuximab-activated NK cells to induce an adaptive T-cell response against tumor antigens expressed by EGFR-positive cancer cells, which could boost the adaptive immune response to EGFR-expressing VR cells." (PMID 38510242, 2024). "We hypothesize that epiregulin (EREG), an epidermal growth factor (EGF) family member derived from hepatic stellate cells (HSCs) and activated by LPS stimulation, is a crucial mediator of HCC progression with epidermal growth factor receptor (EGFR) expression in the tumor microenvironment." (PMID 38673992, 2024). "Hence, we aimed to evaluate if quantifiable parameters could be established for the expression of CD44, EGFR, vimentin, and E-cadherin in terms of predicting tumor aggressiveness and prognostic significance, if any, in OSCC." (PMID 39050298, 2024). "Furthermore, we employed two osimertinib-resistant PDX (PDX-1R, PDX-2R) with no other TKI-resistant related alterations detected except the original EGFR Ex19Del and found the bortezomib combined with osimertinib treatment significantly inhibited the tumor growth." (PMID 38461173, 2024).
tumor (continued). "Interestingly, vascularization seems to depend on tumor type (luminal, basal, or metastatic) while vascular permeability and response to normalizing interventions seem to be associated with the expression of HER2/ERBB2 and EGFR." (PMID 39041892, 2024). "The expression levels of miR-21 are closely related to the regulation of tumor-suppressor genes that are implicated in pivotal cell functions and pathways, such as apoptosis and Ras-Raf-MEK-ERK pathways or/and epidermal growth factor receptor (EGFR), or/and PI3K/AKT signaling pathways, respectively." (PMID 38542378, 2024). "Competing‐risks regression of time to death due to disease for high CD151, no epidermal growth factor receptor (EGFR) mutations group in early or advanced tumour, node, metastasis (TNM, American Joint Committee on Cancer [AJCC]) stage versus others in the Singaporean cohort." (PMID 38982031, 2024). "Additionally, EGFR signaling is closely related to tumor progression and survival." (PMID 39100096, 2024). "Recent progress in understanding cellular signal transduction pathways, including EGFR signaling (which controls cell survival), has identified genetic and regulatory abnormalities that suppress cell death, promote cell proliferation, and induce tumor formation." (PMID 38745775, 2024). "Sidedness was a significant determinant of benefit, with EGFR mAb use associated with PFS prolongation in left-side tumours but not right-sided disease (left-sided PFS HRadj 0.74, 95% CI 0.67–i0.83, p < 0.001; right-sided PFS HRadj 1.03, 95% CI 0.81–1.32, p = 0.798, pinteraction 0.021)." (PMID 38402342, 2024). "Therefore, we assessed the level of EGFR gene amplification in the tumor biopsies." (PMID 38553638, 2024). "Notably, ARAF has a significantly lower kinase activity than BRAF and CRAF, but its overexpression prolonged the duration of MAPK activation, potentially creating conditions conducive to tumor cell survival and the transcription of neuroendocrine markers in the presence of EGFR-TKIs." (PMID 39456595, 2024). "Furthermore, CMTM proteins are capable of regulating the cell cycle, influencing the EGFR-associated pathway and the EMT process, subsequently affecting the proliferation, invasion, and metastasis of tumor cells, indicating their crucial role in tumorigenesis and potential as therapeutic targets." (PMID 38223763, 2024). "The Epidermal Growth Factor Receptor (EGFR) on the cell surface is phosphorylated to form a dimer after binding to its ligand, activating downstream pathways like RAS/RAF/MEK/MAPK and PI3K/AKT, subsequently causing tumor cell proliferation, invasion, and apoptosis." (PMID 38762484, 2024). "This variability could influence the tumor’s response to EGFR-TKI therapy." (PMID 39026979, 2024). "This fusion protein could bind to wild-type EGFR and mutant EGFR-vIII on tumor cells." (PMID 39196415, 2024). "The tumor harbored neither EGFR gene mutation nor ALK gene rearrangement." (PMID 38800395, 2024). "The EMPOWER-Lung 1 trial compared the use of cemiplimab alone to the choice of chemotherapy made by the investigators in patients who were newly diagnosed with advanced NSCLC and tumor PD-L1 expression of at least 50%, along with no EGFR mutations or ALK or ROS1 fusions." (PMID 39027681, 2024). "Therefore, ERBB2/3 and EGFR are ideal tumor-associated antigens, which are suitable for binding with T and B cell activators such as CD3 and CD40 agonists to construct bispecifics, and kill tumor cells by bridging immune cells to tumor." (PMID 38713378, 2024). "Mutations in EGFR and LRP1B could potentially establish an immune niche that fosters tumor growth." (PMID 38370388, 2024). "An LB may be requested at tumor diagnosis or at tumor progression for EGFR TKI-treated patients." (PMID 39409960, 2024). "However, tumours with EGFR mutations and ALK translocations showed no obvious benefit in second-line studies with single-agent checkpoint inhibitor therapy." (PMID 38610927, 2024).
tumor (continued). "Similarly, IL-1B, mostly secreted from tumor-associated macrophages as a pro-inflammatory cytokine, enhances the expression of ELF3 in LUADs with EGFR mutations, leading to the activation of the PI3K/Akt/NF-κB pathway and consequently contributes to tumor progression." (PMID 38983267, 2024). "The crosstalk between MET amplification and the Wnt/β‐catenin signaling pathway was further investigated through gene expression and survival analysis in a cohort of 66 EGFR mutated NSCLC patients without any non‐tumor related diseases, which were carefully selected from the GEO database." (PMID 38867713, 2024). "There were 23 (69.7%) patients who had their EGFR exon 20 insertion mutation confirmed by central test; those whose mutation could not be confirmed centrally had either defective tumor tissue samples or insufficient quantities of DNA for testing." (PMID 39190099, 2024). "Despite the fact that the combined usage of EGFR- and RAS-targeting drugs in clinical practice enhances the effectiveness of cancer treatment, MAPK signaling inhibitors cause cell resistance by activating compensatory feedback loops in tumor cells and tumor microenvironment components." (PMID 38374954, 2024). "EGFR-mutated NSCLC is a cold tumor with a non-inflammatory microenvironment." (PMID 39280252, 2024). "Previous studies have shown that EGFR mutations induce signaling pathways associated with carcinogenesis, such as PI3K/AKT/mTOR, RAS/RAF/MAPK, and JAK/STAT, and promote malignant phenotypes such as proliferation, survival, angiogenesis, invasion, and metastasis of tumor cells." (PMID 38243040, 2024). "However, the ubiquitous presence of EGFR in normal tissues poses a substantial challenge, as therapies targeting EGFR may lead to significant off-tumor toxicity." (PMID 39506843, 2024). "However, on-target off-tumor toxicity is a problem because normal skin cells also contain EGFR." (PMID 39456611, 2024). "Several studies have shown that in NSCLC cells with gene alterations of KRAS G12C, BRAF V600E, EGFR, ALK, or ROS1, dysregulation of the Hippo pathway decreases the initial response to various tyrosine kinase inhibitors, which is associated with resistance of targeted therapy and tumor recurrence." (PMID 38499647, 2024). "By inhibiting EGFR and c-Met signaling functions, either by blocking ligand-induced activation or inducing receptor degradation, amivantamab may disrupt these signaling pathways and prevent tumor growth and progression." (PMID 38916448, 2024). "Inhibiting EGFR could potentially suppress tumor growth and invasion." (PMID 38956591, 2024). "In the communication between normal stromal cells and tumor cells, exosomes may stimulate another signaling pathway, such as nuclear factor κB and epidermal growth factor receptor signaling pathway, which also play a critical role in tumor proliferation and migration." (PMID 39188515, 2024). "The variation in results compared to previous studies may be attributed to the small sample size, differences in the type of specimen the measurement technique for EGFR expression., type of antibodies used, different criteria for EGFR positivity or biological nature of the tumor." (PMID 39405290, 2024). "However, heterodimerized T-BsAbs required both tumor-binding moieties for effective antitumor effectiveness, as loss of either EGFR or HER2 Fabs failed to exhibit a significant benefit in tumor control." (PMID 38650005, 2024). "Tumor mutation status also impacts on development of brain metastases, but was not included in our study due to absence of relevant mutations, in particular EGFR." (PMID 39331216, 2024). "Hence, we hypothesized that C22orf46 knockout may promote cell surface presentation of the tumor antigens Her2, EGFR, and EpCAM, providing an explanation for the observed phenotype." (PMID 38228372, 2024).
tumor (continued). "The loss of tumour suppressor miRNAs, which typically regulate mRNAs that may have oncogenic potential, such as miR-31, which inhibits CDKN2A/B and miR-34a, affecting EGFR protein levels, contributes to cell proliferation, apoptosis resistance, and subsequent disease progression." (PMID 38674436, 2024). "On a speculative approach, we may suppose that in non-mutated (wild type) KRAS PDAC, EGFR amplification or mutation can be a tumor driver and, therefore, requires a different targeted approach." (PMID 38607041, 2024). "Potential tumor markers, such as Cox-2, Ki-67, and EGFR, significantly correlate with tumor characteristics; thus, they could reveal prognosis and, in the cases of Cox-2 and EGFR, therapeutic potential." (PMID 38785565, 2024). "As a transmembrane receptor, EGFR is activated via autophosphorylation by tyrosine kinase after being activated by an extra-cellular signal, which subsequently results in the activation of a series of downstream intracellular pathways that promote tumor proliferation and metastasis." (PMID 38774407, 2024). "For EGFR mutation status classifiers trained on TCGA and evaluated on CCLE, we saw that the area under the precision-recall curve (AUPR) on cell lines was slightly worse than on held-out tumor samples but comparable across regularization levels/LASSO parameters." (PMID 39776849, 2024). "Therefore, anti-EGFR monoclonal antibodies have potential synergistic effects with immune checkpoint inhibitors, and their combined use can stimulate both innate and adaptive immune systems to kill tumor cells." (PMID 38809459, 2024). "The SUVmax of the primary tumor could indicate the EGFR status." (PMID 39722096, 2024). "In addition, evidence has determined that the stable attachment of nimotuzumab requires bivalent binding, so nimotuzumab selectively binds to tumor cells expressing moderate to high EGFR levels, thereby protecting healthy cells with low levels of EGFR, and thus severe skin toxicity does not occur." (PMID 38962426, 2024). "Therefore, anti-EGFR antibodies may be effective for the treatment of cancers in which EREG controls tumor growth and drug resistance in an autocrine or paracrine way." (PMID 38398101, 2024). "To validate the inhibitory role of CD47 expression in neutrophil-mediated killing of tumor cells, we screened a large number of tumor cell lines and evaluated the expression levels of common tumors associated antigen targets, including CD47, as well as the expression of EGFR, EpCAM, and HER2." (PMID 37444515, 2023). "In line with this, tumors with alterations in the ErbB family genes (and particularly EGFR) develop a non-inflamed tumor microenvironment, which could be due to a low tumor mutational burden (TMB)." (PMID 37370859, 2023). "In November 2020, within the period used to define the COVID-19 cohort for this analysis, the European Medicines Agency approved nivolumab plus ipilimumab with two cycles of chemotherapy for 1L treatment of mNSCLC, in adults whose tumours have no sensitising EGFR mutation or ALK translocations." (PMID 37386452, 2023). "Furthermore, it could be shown that the VHH retained its specificity towards its target the anti-epidermal growth factor receptor (EGFR) by blocking experiments with unlabeled cetuximab, which reduced the tumor uptake by nearly half." (PMID 37908729, 2023). "EGFR membrane expression on tumor cells was among the biomarkers analyzed on the TMAs prepared from patients’ biopsies since several evidences previously demonstrated that EGFR activation can induce VEGF expression within the tumor microenvironment thus increasing OC angiogenesis." (PMID 37041632, 2023).